DIRAS1 (DIRAS family GTPase 1)
Description:
Displays low GTPase activity and exists predominantly in the GTP-bound form.
Synonyms: Rig; GBTS1; Di-Ras1
Tractability: Small molecule: a structure with a bound ligand is known; it has a binding pocket of medium quality. Antibody: UniProt places it where antibodies can reach, with high confidence; its Gene Ontology location is reachable by antibodies, with high confidence; the Human Protein Atlas places it where antibodies can reach. PROTAC: ubiquitination databases record sites on it; its protein half-life has been measured.
Gene: Protein-coding gene on chromosome 19 (2,714,566 to 2,721,438, reverse strand). Ensembl gene ENSG00000176490.
Subcellular location: Cell membrane
Subcellular location (Human Protein Atlas): Plasma membrane; Vesicles; Nucleoplasm
Gene Ontology:
Molecular function: GTP binding; GTPase activity; mitogen-activated protein kinase binding; protein binding
Biological process: positive regulation of MAP kinase activity; small GTPase-mediated signal transduction; signal transduction
Cellular component: plasma membrane; membrane
Genetic constraint (gnomAD): Loss-of-function variants: 4 observed, 10.09 expected, observed/expected ratio (o/e) 0.4, 90% interval 0.19 to 0.91. The upper end of that interval is the gene's LOEUF score, 0.91, which puts it in group 3 of 6, group 1 being the genes least tolerant of losing a copy. Missense variants: 212 observed, 279.48 expected, observed/expected ratio (o/e) 0.76, 90% interval 0.68 to 0.85. Synonymous variants: 128 observed, 123.04 expected, observed/expected ratio (o/e) 1.04, 90% interval 0.9 to 1.21.
Homologues: Orthologues: chimpanzee DIRAS1 (100% identical), pig DIRAS1 (98% identical), dog DIRAS1 (97% identical), mouse Diras1 (94% identical), rat Diras1 (94% identical), tropical clawed frog diras1 (89% identical), zebrafish diras1b (83% identical), zebrafish diras1a (79% identical). Paralogues in human: DIRAS2 (79% identical), DIRAS3 (46% identical), RASD2 (43% identical), RASD1 (40% identical), RAP2A (39% identical), RAP2B (38% identical), RAP2C (38% identical), RAP1A (37% identical), RAP1B (37% identical), RRAS2 (36% identical), RIT2 (35% identical), RRAS (35% identical), and 23 more.
Diseases named in the same sentence as DIRAS1 in open-access papers:
DIRAS1 is named in the same sentence as 22 diseases in open-access papers, as found by Europe PMC text mining. Sharing a sentence is not in itself a finding about the gene and the disease. The quoted sentences say what the papers report.
colorectal cancer (4 papers, 2017 to 2025). A primary or metastatic malignant neoplasm that affects the colon or rectum. "(C) The methylation status of the CpG site (cg05228284, HM450) is correlated to loss of/reduced DIRAS1 expression in 234 cases of colorectal cancer." (PMID 28491151, 2017). "In TCGA database, the promoter region methylation was inversely associated with DIRAS1 expression in colorectal cancer." (PMID 28491151, 2017). "DIRAS1 is frequently methylated in human colorectal cancer and the expression of DIRAS1 is regulated by promoter region methylation." (PMID 28491151, 2017). "DIRAS1 induced apoptosis and inhibited cell proliferation, migration, and invasion in colorectal cancer." (PMID 28491151, 2017). "DIRAS1 inhibits cell proliferation, migration, and invasion and induces apoptosis in colorectal cancer cells." (PMID 28491151, 2017). "Methylation of DIRAS1 is a marker of poor prognosis in human colorectal cancer." (PMID 28491151, 2017). "DIRAS1 suppresses colorectal cancer cell xenograft growth in vivo." (PMID 28491151, 2017). "DIRAS1 has been described as a potential tumor suppressor in human glioblastomas and esophageal cancer, and downregulation of the DIRAS1 predicts poor prognosis in esophageal squamous cell carcinoma; however, its role in colorectal cancer remains unclear." (PMID 28491151, 2017). "The results demonstrate that DIRAS1 inhibits colorectal cancer cell migration." (PMID 28491151, 2017). "It suggests that DIRAS1 suppresses colorectal cancer cell growth." (PMID 28491151, 2017). "The results demonstrated that DIRAS1 inhibits cell viability in colorectal cancer cells." (PMID 28491151, 2017). "The results suggest that DIRAS1 suppresses colorectal cancer cell growth." (PMID 28491151, 2017). "The result suggests that DIRAS1 inhibits cell invasion in colorectal cancer." (PMID 28491151, 2017). "Therefore, we analyzed the epigenetic regulation and function of DIRAS1 in human colorectal cancer." (PMID 28491151, 2017). "Finally, DIRAS1 suppressed colorectal cancer cell xenograft growth in nude mice." (PMID 28491151, 2017). "Methylation of DIRAS1 was detected in 47.3% (69/146) of primary colorectal cancers, and no methylation was found in 50 cases of non-cancerous colonic tissue samples." (PMID 28491151, 2017).
esophageal squamous cell carcinoma (4 papers, 2017 to 2025). Esophageal squamous cell carcinoma (ESCC) is a type of esophageal carcinoma (EC) that can affect any part of the esophagus, but is usually located in the upper or middle third. "In esophageal squamous cell carcinoma (ESCC), reduced DIRAS1 expression correlates with advanced clinical stage, lymph node metastasis, and poor overall survival." (PMID 40723377, 2025).
breast carcinoma (3 papers, 2017 to 2024). "The expression levels of DIRAS1 were found to be reduced in human breast cancer and esophageal cancer." (PMID 28491151, 2017). "The expression of DIRAS1 is downregulated in most types of breast cancer." (PMID 36338974, 2022).
cervical cancer (3 papers, 2024 to 2025). A primary or metastatic malignant neoplasm involving the cervix. "In summary, this study will examine the anti-cancer function of DIRAS1 and its unique expression pattern in cervical cancer, and analyze the epigenetic regulatory mechanisms underlying the down-regulation of its expression." (PMID 38372700, 2024). "In addition, statistical analysis of the data showed that low expression of DIRAS1 was associated with high pathological stage in cervical cancer patients." (PMID 38372700, 2024). "Similar tumor-suppressive functions have been observed in cervical cancer, where DIRAS1 downregulation facilitates tumor progression while its overexpression inhibits proliferation, migration, and invasion." (PMID 40723377, 2025). "In this study, we investigated the role of DIRAS1 expression in the proliferation, growth and motility of cervical cancer cells cultured in vitro using knockdown and exogenous overexpression of DIRAS1 in C33A and SiHa cells." (PMID 38372700, 2024). "Compared with normal cervical tissues, DIRAS1 mRNA levels were significantly lower in cervical cancer tissues." (PMID 38372700, 2024). "In conclusion, DIRAS1 exerts a significant anti-oncogenic function and its expression is significantly downregulated in cervical cancer cells." (PMID 38372700, 2024). "In contrast, in cervical cancer tissues, DIRAS1 protein expression was not only significantly reduced, but the nucleus accumulation also disappeared significantly." (PMID 38372700, 2024). "In summary, DIRAS1 exerts a significant anti-oncogenic function and its expression is significantly downregulated in cervical cancer cells." (PMID 38372700, 2024). "DIRAS1 protein expression was also significantly reduced in cervical cancer tissues compared with para-cancerous tissues." (PMID 38372700, 2024). "Given the anti-oncogenic role of DIRAS1 and its specific expression downregulation in cervical cancer cells, we further explored the major epigenetic mechanisms that regulate the downregulation of DIRAS1 expression in cancer cells." (PMID 38372700, 2024). "The m6A modification may be a key mechanism to regulate DIRAS1 mRNA stability and protein translation efficiency in cervical cancer." (PMID 38372700, 2024). "In addition, DIRAS1 expression level in tumor tissues was significantly negatively correlated with the pathological grades of cervical cancer patients." (PMID 38372700, 2024). "Furthermore, the expression level of DIRAS1 in tumor tissues was significantly negatively correlated with the pathological grade of cervical cancer patients." (PMID 38372700, 2024).
glioblastoma (3 papers, 2017 to 2024). The most malignant astrocytic tumor (WHO grade IV). "Functionally, overexpression of DIRAS-1 and -2 in glioblastoma cells translated into significantly higher sensitivity to lomustine treatment." (PMID 34680261, 2021). "Since there were reports on the role of DIRAS-3, another family member of small Ras-GTPases, in resistance to chemotherapeutic agents, we were interested to evaluate whether DIRAS-1 or -2 could mediate chemoresistance in glioblastoma cells." (PMID 34680261, 2021). "However, whether the mechanism of DIRAS-1-induced autophagic cancer cell death reported in ovarian cancer cells also applies to glioblastoma cells needs to be elucidated in additional analyses." (PMID 34680261, 2021).
ovarian carcinoma (2 papers, 2021 to 2024). A malignant neoplasm originating from the surface ovarian epithelium. "Sutton and colleagues showed that expression of DIRAS-1 and DIRAS-2 is downregulated in ovarian cancer and associated with decreased disease-free and overall survival." (PMID 34680261, 2021).
astrocytic tumor (1 paper, 2021). A glial tumor of the brain or spinal cord showing astrocytic differentiation. "In our analyses we confirmed the downregulation of DIRAS-1 mRNA expression in IDH-mutant astrocytic tumors, but also found DIRAS-1 transcript levels strongly reduced in eight out of 10 IDH-mutant and 1p/19q-codeleted oligodendroglioma samples." (PMID 34680261, 2021). "However, DNA hypermethylation alone may not be sufficient to down-regulate DIRAS-1, as we also observed reduced DIRAS-1 expression in IDH-wild-type astrocytic tumors in the absence of promoter hypermethylation." (PMID 34680261, 2021).
attention deficit-hyperactivity disorder (1 paper, 2014). A disorder characterized by a marked pattern of inattention and/or hyperactivity-impulsivity that is inconsistent with developmental level and clearly interferes with functioning in at least two settings (e.g. at home and at school). "DIRAS1 is likely to be a neural tumor suppressor, and DIRAS2 is associated with an adult form of attention deficit hyperactivity disorder." (PMID 24523945, 2014).
brain tumors (1 paper, 2021). "We investigated the genes DIRAS-1 and DIRAS-2 in terms of their regulation and functional relevance in brain tumors (gliomas)." (PMID 34680261, 2021).
cervical squamous cell carcinoma (1 paper, 2024). A squamous cell carcinoma arising from the cervical epithelium. "We analyzed RNA-Seq data of cervical squamous cell carcinoma and endocervical adenocarcinoma (CESC)-related tissues from the TNMplot database (tnmplot.com), and found that DIRAS1 mRNA levels were significantly reduced in CESC tissues (N = 304), compared to normal cervical tissues." (PMID 38372700, 2024).
glioma (1 paper, 2021). A benign or malignant brain and spinal cord tumor that arises from glial cells (astrocytes, oligodendrocytes, ependymal cells). "Altogether, these data indicate that promoter heterochromatinization in gliomas relevantly contributes to DIRAS-1 and DIRAS-2 transcriptional downregulation." (PMID 34680261, 2021). "We here investigated the exact mechanisms of DIRAS-1 and -2 regulation in gliomas and its functional implications in terms of cell proliferation and sensitivity to DNA alkylating chemotherapy." (PMID 34680261, 2021). "Moreover, a significant down-regulation of DIRAS-1 and -2 was detected in glioma data obtained from the TCGA database." (PMID 34680261, 2021). "Thus, we subsequently analyzed whether histone modifications may also contribute to DIRAS-1 and -2 downregulation in gliomas." (PMID 34680261, 2021). "All these findings provide evidence for downregulation of DIRAS-1- and DIRAS-2 as a mechanism of chemoresistance in gliomas." (PMID 34680261, 2021). "In contrast, regulation and function of DIRAS-1 and -2 in gliomas has not been addressed in detail so far." (PMID 34680261, 2021). "However, we did not observe an impact of DIRAS-1 over-expression on cell proliferation in the two glioma cell lines analyzed." (PMID 34680261, 2021). "We investigated the expression of DIRAS-1 transcripts and detected decreased mRNA levels (<0.5-fold relative to non-neoplastic brain tissue) in 22 out of 34 gliomas (65%) and intermediate mRNA levels (between 0.5 and <1 relative to non-neoplastic brain tissue) in eight out of 34 gliomas (24%)." (PMID 34680261, 2021).
Juvenile Myoclonus Epilepsy (1 paper, 2024). "Juvenile Myoclonus Epilepsy (JME), an inherited epilepsy, is caused by a deletion in the DIRAS1‐gene in young Rhodesian Ridgebacks and characterized by frequent myoclonic twitches." (PMID 39473196, 2024).
metastatic tumors (1 paper, 2021). "DIRAS1, FBXL16, TP53I11, TFF2, and ZNF467 were upregulated in both metastatic tumors and GHSROS-overexpressing PC3 and LNCaP cells, while AASS, CHRDL1, CNTN1, IFI16, and MUM1L1 were downregulated." (PMID 33585078, 2021).
tumor (7 papers, 2014 to 2025). "DIRAS1 has been implicated in the regulation of tumor cell proliferation, migration, and chemoresistance in multiple solid malignancies." (PMID 40723377, 2025). "DIRAS1, a small GTPase within the Ras superfamily, has been previously reported to function as a tumor suppressor in various human malignancies." (PMID 40723377, 2025). "Collectively, these data suggest that DIRAS1 functions as a pro-oncogenic factor in CRC by promoting tumor cell proliferation and migration." (PMID 40723377, 2025). "WB further confirmed significantly elevated DIRAS1 protein expression in CRC tumor tissues, particularly in NRT samples." (PMID 40723377, 2025). "DIRAS family GTPase 1 (DIRAS1) has been reported as a potential tumor suppressor in other human cancer." (PMID 38372700, 2024). "DiRas1 is a Ras family member that acts as a tumor suppressor in many types of cancer." (PMID 34222337, 2021). "Collectively, our results suggest that DIRAS1 is a tumor suppressor in human CRC." (PMID 28491151, 2017). "Immunofluorescence staining further confirmed the co-enrichment of DIRAS1 and PHB1 in CRC tumor tissues relative to adjacent and distant normal tissues." (PMID 40723377, 2025). "The role of DIRAS1, a RAS superfamily member with reported tumor-suppressive functions in various cancers, remains poorly defined in CRC." (PMID 40723377, 2025). "Silencing DIRAS1 reduced the IC50 of OXA in vitro and increased tumor sensitivity to OXA in vivo." (PMID 40723377, 2025). "Moreover, DIRAS1 and PHB1 protein levels were positively correlated in tumor samples, with linear regression yielding an R2 of 0.7857 (p = 0.0480)." (PMID 40723377, 2025). "Silencing DIRAS1 reduced OXA IC50 and enhanced tumor sensitivity both in vitro and in vivo." (PMID 40723377, 2025). "The low-level expression of the DIRAS1 protein in tumor tissues may be the main reason for its lack of nuclear localization." (PMID 38372700, 2024). "DIRAS1 is a well-known tumor suppressor and the ability of DIRAS1 to significantly diminish the prenylation of RAC1B, and to a lesser extent RAC1, provides a new mechanism through which DIRAS1 may inhibit oncogenic signaling by these small GTPases." (PMID 37059183, 2023). "Bergom and colleagues more closely analyzed the tumor suppressive mechanisms of DIRAS-1 and showed that DIRAS-1 binds to the noncanonical guanine nucleotide exchange factor SmgGDS (Rap1 GTPase-GDP dissociation stimulator 1 = RAP1GDS1) and acts similarly to a dominant-negative small GTPase." (PMID 34680261, 2021).
cancer (5 papers, 2017 to 2024). A tumor composed of atypical neoplastic, often pleomorphic cells that invade other tissues. "The focus of this study is on the regulatory mechanisms underlying the downregulation of DIRAS1 expression in cancer cells." (PMID 38372700, 2024). "The results of this study, in combination with those of other studies, suggest that DIRAS1 has a potent cancer inhibitory effect." (PMID 38372700, 2024). "Stenotrophomonas, an opportunistic pathogen with increased colonization/infection in cancer patients, exhibited extensive positive associations with the hypermethylation of genes, including multiple TSGs in CRC, such as ESR1, RASSF5, DIRAS1, CADM1, ST5, GJB2, FAM172A, and HIVEP3." (PMID 38840170, 2024). "In the 16 cancer samples with low level expression of DIRAS1, 12 cases were methylated." (PMID 28491151, 2017). "Based on this result, we hypothesized that both DNA methylation and histone acetylation might be involved in the transcriptional regulation of DIRAS1 in cancer cells, with DNA methylation hindering DIRAS1 transcription and histone acetylation promoting DIRAS1 transcription." (PMID 38372700, 2024). "In addition, in para-carcinoma tissues, DIRAS1 protein showed significant nucleus accumulation." (PMID 38372700, 2024). "Low-level expression of DIRAS1 was found in 16 of 26 (61.5%) cancer samples compared to adjacent non-cancerous tissue samples." (PMID 28491151, 2017). "However, western blot results showed that DIRAS1 protein levels were not significantly altered after inhibitor treatment, suggesting the existence of a more critical post-transcriptional regulatory mechanism for DIRAS1 that further controls the low-level expression of DIRAS1 protein in cancer cells." (PMID 38372700, 2024).
DIRAS1 also shares sentences with these, for which no sentence is quoted: lymph node metastasis (2 papers); renal cell carcinoma (2); endocervical adenocarcinoma (1); esophageal cancer (1); infection (1); neural tumors (1); oligodendroglioma (1).